LEP (leptin)
Diseases named in the same sentence as LEP in open-access papers (continued):
Sharing a sentence is not in itself a finding about the gene and the disease.
Obesity (continued). "Obesity alone does not cause knee OA, and leptin might be involved in OA because without leptin, obesity itself does not predispose an individual to OA." (PMID 22046520, 2011). "Furthermore, the excessive secretion of leptin and/or decreased production of adiponectin by adipocytes in obesity may either directly affect bone formation or indirectly affect bone resorption through up-regulated proinflammatory cytokine production." (PMID 21676245, 2011). "Furthermore, it has been observed that the administration of exogenous leptin fails to reduce adiposity significantly in most cases of human obesity that are characterized by increased adipocyte leptin content and high circulating leptin levels, reflecting a state of leptin resistance." (PMID 21760816, 2011). "Obviously the positive effect of mechanical loading of increased body weight could not overcome the detrimental effect of leptin-deficiency (or possibly obesity) on bone in these mice." (PMID 21676245, 2011). "However, use of recombinant leptin for obesity has been relatively ineffective." (PMID 21526991, 2011). "An experimental study showed that extreme obesity arising from impaired leptin signaling induced alterations in subchondral bone morphology without increasing the incidence of knee OA, suggesting that body fat, in and of itself, might not be a risk factor for joint degeneration." (PMID 22046520, 2011). "The failure of fructose to effectively suppress ghrelin (impaired satiety), along with the reduced insulin and leptin concentrations, could lead to an increased caloric intake and ultimately contribute to obesity, during chronic consumption of diets high in fructose." (PMID 20798765, 2010). "Therefore, understanding the mechanisms by which leptin and its targets influence energy balance could lead to new therapeutic targets for obesity." (PMID 20808936, 2010). "We observed that the absence of leptin leads to obesity even in the context of iNOS deficiency." (PMID 20532036, 2010). "Therefore, chronic elevations of ghrelin levels and/or reductions of leptin levels may attribute to the development of obesity." (PMID 20414467, 2010). "Currently, the effect of leptin signaling in the respiratory system remains controversial, possibly due to the fact that much of the existing knowledge derives from animal models of obesity (e.g. ob/ob model) that cannot identically represent the complex biological state of human obesity." (PMID 21040518, 2010). "The mechanisms underlying the relationship between obesity and asthma have not been fully established yet, however, experimental evidence suggests that changes in adipose-tissue derived hormones, including leptin, as well as other factors, are possibly implicated." (PMID 21040518, 2010). "For example, the ob/ob [obese], db/db [diabetes] and the Zucker diabetic fatty rat (ZDF) have mutations either in the leptin gene (ob/ob) or in the leptin receptor (db/db) which causes over-eating obesity, unlike the natural history of the disease in humans where leptin is seldom implicated." (PMID 20398338, 2010). "Any leptin-mediated effects of obesity may be complemented by a mechanical loading effect in the superior compartment, as suggested by the fact that the consistent associations between obesity measures and JSN in this compartment remained positive after adjustment for leptin." (PMID 20482813, 2010). "The results suggested that compound 1a could improve leptin resistance induced by obesity." (PMID 20482839, 2010). "Indeed, leptin is clearly significant in pubertal development and progression in humans; congenital leptin deficiency due to mutations in either the leptin gene or the leptin receptor gene, is associated with early-onset obesity and no pubertal development." (PMID 21176234, 2010). "In addition, the BMI-dependent effect of leptin for the expression of TIMP-2 and MMP-13 may explain why obesity is associated with an increased risk for OA." (PMID 20534145, 2010).
Obesity (continued). "Although the prevalence of hip OA is lower than that of knee OA, and some risk factors such as obesity appear not to have equal effects on hip and knee OA, effects of leptin on hip and knee OA may be different." (PMID 20482813, 2010). "Our present findings may have particular importance for designing new therapies for BC and other cancer types (that is, endometrial cancer, colon cancer, prostate cancer, and so forth) where obesity and leptin signaling have also been related to their incidence and growth." (PMID 19531256, 2009). "Recent literature indicates that circulating leptin concentrations are possibly increased by hypoxic conditions in humans, suggesting a link to the obstructive sleep apnea syndrome (OSAS), a disease characterized by recurrent night apneic periods, which is strongly associated with obesity." (PMID 19946426, 2009). "Indeed, lack of leptin in mice with a mutation in the gene encoding leptin, or absence of functional leptin receptor (db/db mice) results in obesity and many associated metabolic complications such as insulin resistance." (PMID 20030801, 2009). "However, whether there is a direct relationship between leptin and ovarian cancer cannot be conclusively stated as increased leptin and ovarian cancer may both be secondary consequences of obesity." (PMID 19765303, 2009). "Therefore, we can speculate that recurrent oxygen desaturations in OSAS patients may play a major role in the regulation of leptin concentrations disregarding the influence of obesity." (PMID 19946426, 2009). "Furthermore, chronic leptin treatment in diet-induced obese rats accelerates dietary obesity." (PMID 19750222, 2009). "Moreover, additional factors, such as leptin and oxidative stress, may contribute to sympathetic drive and hypertension in obesity." (PMID 19811354, 2009). "We investigated whether an Irvingia gabonensis seed extract (IGOB131) would provide a more beneficial comprehensive approach influencing multiple mechanisms and specifically PPAR gamma, leptin and adiponectin gene expressions, important in anti-obesity strategies." (PMID 19014517, 2008). "Hence, we speculated that the reason for the obesity in cloned mice is the leptin resistance induced by an excess of the Crp protein." (PMID 18398451, 2008). "If OSA is truly associated with increased leptin serum levels independent of obesity, the causal link remains unclear." (PMID 18828917, 2008). "In lean, but not in obese human skeletal muscle, leptin is able to stimulate fatty acid oxidation, suggesting that triglyceride accumulation and lipotoxicity in obesity could be caused by changes in the leptin signaling cascade." (PMID 18941624, 2008). "Given the importance of leptin in body weight regulation, this study was undertaken to determine whether variations in the coding sequence (CDS) or promoter region of SOCS3 are associated with early onset obesity in a German population." (PMID 17445271, 2007). "However, more work is needed to establish whether the high levels of leptin in obesity have a protective effect or contribute to islet destruction in vivo." (PMID 17521427, 2007). "The group found that mean leptin levels were three-fold higher in patients who survived the episode than in non-survivors, and concluded that in addition to its function as an anti-obesity factor, leptin may play a role in a severe stress state such as acute sepsis." (PMID 17349033, 2007). "Interestingly, there were also differences in comparisons between the Low-Fat and Obesity-Resistant mice despite their similar body weights, such as a trend toward higher palpable MT incidence and higher fat pad weights and serum leptin levels in the Obesity-Resistant mice." (PMID 18162139, 2007).
Obesity (continued). "Identifying the hypothalamic leptin/melanocortin pathway as critical in many cases of monogenic obesity has permitted targeted, hypothesis-driven experiments to be performed, and has implicated new candidates as causative for previously uncharacterized clinical cases of obesity." (PMID 17196040, 2006). "Alternatively, obesity could be a marker for other effecting mechanisms, such as leptin resistance, and the diverging weight curves would then suggest that the beneficial effects on risk factors could be due to differences between diets regarding promotion of leptin resistance." (PMID 17081292, 2006). "Similarly, there was no suggestion that the risk estimates associated with the leptin SNPs varied between persons of normal BMI, grade 1, or grades 2 and 3 obesity (data not shown)." (PMID 16160698, 2005). "Increased serum leptin levels in obesity and metabolic syndrome support the view that these disorders are in fact low-grade systemic inflammatory diseases, characterized by increased concentrations of proinflammatory cytokines like interleukin-6, tumor necrosis factor-α and leptin." (PMID 15599390, 2004). "Fourth, while leptin-deficient mice provide a robust and reproducible platform for investigating metabolic-driven injury, this genetic model may not fully capture the multifactorial nature of human obesity seen in diet-induced obesity (DIO) models." (PMID 41516387, 2026). "The global obesity epidemic drives a cascade of lipid metabolism disorders, including hyperlipidemia, non-alcoholic fatty liver disease (NAFLD), and leptin resistance." (PMID 41588470, 2026). "This contrasts with homozygous/bi-allelic carriers of LoF mutations in other genes in the leptin-melanocortin signalling pathway -LEP, LEPR, POMC, PCSK1 and MC4R-who almost inevitably develop severe obesity at an early age." (PMID 41386534, 2026). "Additionally, similar to the concept of insulin or leptin resistance, obesity and metabolic disturbances may lead to a state of irisin resistance, wherein elevated circulating levels reflect a compensatory response to maintain glucose and metabolic homeostasis." (PMID 41457869, 2026). "PTP1B came into limelight as a primary target responsible for the progression of abnormal conditions like obesity, insulin resistance, and NAFLD, which is a down-regulator of leptin and insulin pathways." (PMID 40356976, 2025). "Obesity‐related type I inflammatory cytokines (e.g., IFN‐γ, TNF, leptin, insulin, and palmitic acid) promote TAM PD‐1 expression through mechanistic target of rapamycin complex 1 (mTORC1) and glycolysis‐dependent mechanisms." (PMID 41267926, 2025). "Results indicated that B. mix could both prevent and reduce established obesity by decreasing weight gain, fat accumulation, adipocyte size, and immune cell infiltration in adipose tissue, while improving lipid profiles and regulating leptin and cytokine secretion." (PMID 40549339, 2025). "There is a feedback loop explaining the increased production of multiple inflammatory cytokines (IL-6, IL-12, TNF-α) from leptin and the increased expression of leptin from others (e.g., IL-1, TNF-α), leading to a chronic inflammatory state due to obesity." (PMID 41227378, 2025). "Specifically, LEP expression was upregulated by 5.2-fold in the OBS treatment culture, suggesting potential modulatory effects of folic acid on obesity-related adipocyte function." (PMID 40292473, 2025). "Severe obesity is characterized by abnormal expansion of WAT, which acts as an endocrine organ capable of secreting various adipokines, including leptin." (PMID 41441006, 2025). "In the case of DIO, as our data suggest that HFD feeding increased the activity of Arc non-LepR neurons, leptin, although at an increased level, may not be able to exert a direct inhibitory action on non-LepR neurons and therefore fails to reduce obesity in DIO, causing phenotypic leptin resistance." (PMID 40540394, 2025).
Obesity (continued). "The interaction between APLNR, VEGF, leptin, and DNA methylation creates a complex network in the placenta that influences the development and progression of GDM and obesity." (PMID 41302116, 2025). "In our data, MHO subjects also displayed higher leptin levels than MUHNW subjects, suggesting a dominant role for obesity." (PMID 40362681, 2025). "Given leptin’s central role in energy balance and endocrine regulation, these findings further support the therapeutic potential of CKDB-322 in obesity management." (PMID 40869311, 2025). "Obesity promotes a pro-inflammatory environment by increasing TNF-α, IL-6, IL-1, leptin, and resistin levels that reach the bloodstream and generate a systemic inflammatory state." (PMID 40067600, 2025). "Genes downregulated in SHBG-stimulated adipocytes included LEP, LEPR, FLST3, CRTC2, and ID3, all of which are known to contribute to obesity-induced inflammation and insulin resistance." (PMID 40532849, 2025). "When the obesity group (n = 60) was classified according to the obesity class, the metaflammation markers under the study, leptin (p < 0.001), TNF-α (p = 0.007), and Wnt5a (p = 0.001), showed a significant increase with the higher obesity class." (PMID 39837875, 2025). "Recent pharmacogenomic studies have further highlighted therapeutic opportunities for monogenic obesity, particularly through MC4R agonists and leptin replacement strategies." (PMID 41302083, 2025). "Obesity triggers systemic inflammation (e.g., increased CRP, IL-6, and leptin) and reduces vitamin D availability, both of which are implicated in MS development." (PMID 40909065, 2025). "Recent reports confirm that Lactobacillus can decrease the levels of LDL-C and TC in obese adults and mitigate obesity in HFD-induced rats by improving lipid metabolism and regulating leptin and adiponectin levels." (PMID 40565656, 2025). "In women with concurrent obesity, obstructive sleep apnea (OSA), and endometrial cancer, adipokines (leptin/adiponectin) and estrogen pathways collectively regulate metabolic dysfunction." (PMID 41357522, 2025). "The paradoxical finding of high serum FGF21 levels in men with obesity is consistent with a state of FGF21 resistance, as shown in mice, similar to what occurs with leptin." (PMID 39885510, 2025). "It will be important to understand how obesogenic diets and leptin resistance reshapes these ARC pathways, leading to hyperphagia and obesity." (PMID 41251447, 2025). "Results from our diet-induced obesity study (DIO), in which C57BL/6 mice were fed a high-fat diet ± AHE, showed improved glucose clearance and serum leptin levels, as well as adiposity." (PMID 40699617, 2025). "In summary, while traditional overweight and obesity intervention focus on diet and PA, multi-component interventions focusing on EE, which involve CT and Social Training (ST) may provide additional benefits by improving leptin sensitivity and enhancing neural plasticity." (PMID 40607230, 2025). "In obesity, its hypothalamic upregulation impairs insulin receptor- and STAT3-mediated leptin pathways, particularly in proopiomelanocortin neurons." (PMID 40699839, 2025). "It appears that leptin binds to circulating C-reactive Protein (CRP), an inflammatory marker that is increased in obesity." (PMID 38778593, 2025). "In cancer, obesity-induced expression of growth factors, inflammatory cytokines (e.g., IL-6 and TNF-α), and adipokines (e.g., leptin) can induce dysregulation PI3K/AKT/mTOR signaling pathway, to induce cancer progression and predict a poor prognosis." (PMID 40863244, 2025). "In fact, obesity can impact serum concentrations of pro-inflammatory mediators [such as IL-6, CRP, TNF-α, resistin, and leptin] and anti-inflammatory mediators (Adiponectin and IL-10) in individuals with periodontitis." (PMID 40422620, 2025). "Obviously, olivetol decreased leptin levels in both C57Bl6 mice fed an HFD and db/db mice that developed obesity spontaneously." (PMID 39857767, 2025).
Obesity (continued). "In conclusion, this study identified three markers, Wnt5a, leptin, and TNF-α which were significantly higher in women with obesity and positively correlated with each other." (PMID 39837875, 2025). "This study examined Rhein’s renoprotective effects in high-fat diet (HFD)-induced ORG mice and leptin-stimulated podocytes, focusing on P2X7R/NLRP3 inhibition to provide insights for obesity-related kidney diseases." (PMID 41586196, 2025). "In obesity-related PCOS, heightened leptin levels and increased circulating TNF-α further alter EV cargo composition towards pro-inflammatory and anti-differentiation patterns, worsening oocyte maturation abnormalities." (PMID 41010046, 2025). "The intricate relationship between obesity and VTE is influenced by adipokines such as leptin, which exerts a paradoxical effect on thrombosis." (PMID 41226331, 2025). "Basic clusters include metabolic foundations (obesity, adipose tissue, FGF21) and adipokine-centered subjects (adiponectin, leptin, NASH)." (PMID 40868109, 2025). "The main inflammatory players in obesity are pro-inflammatory cytokines such as TNF-α, IL-6, and C-Reactive Protein (CRP), as well as adipokines such as leptin, adiponectin, resistin, among others secreted by adipose tissue." (PMID 41373779, 2025). "In turn, individuals with obesity exhibited lower CAMKK1, lower glycemia, lower TNFα and higher ghrelin and leptin in comparison to patients with T2DM." (PMID 40965347, 2025). "As previously discussed, with obesity and T2DM, leptin levels increase and adiponectin levels decrease, leading to higher LARs." (PMID 40722840, 2025). "By integrating insights from leptin signaling and GPCR pharmacology, future research for developing more effective and sustainable anti-obesity interventions is growing brighter." (PMID 41016636, 2025). "Elevated pro-inflammatory mediators in obesity, including TNF-α, leptin, and resistin, disrupt cellular glucose uptake via suppression of insulin receptor signaling, culminating in hyperglycemia and diabetes." (PMID 41246338, 2025). "In line with a role for the leptin-melanocortin system in energy homeostasis, individuals with genetic defects in leptin signaling, POMC, or MC4R present with increased appetite and obesity." (PMID 41251447, 2025). "All in all, the metabolic deterioration from obesity healthy to obesity abnormal correlated with altered levels of hs-CRP, leptin, adiponectin, chemerin, and IL-18." (PMID 39940942, 2025). "Furthermore, obesity is associated with chronic inflammation and elevated levels of cytokines, such as TNF-α, interleukin-1 beta (IL-1β), interleukin-6 (IL-6), and adipokines (e.g., leptin), which support tumor cell proliferation, angiogenesis, and TME modulation." (PMID 41228278, 2025). "Interestingly, high leptin levels in obesity may actually worsen leptin resistance." (PMID 41150735, 2025). "This immunostimulatory role becomes pathological in obesity, where hyperleptinemia coexists with leptin resistance—a state exacerbated by pro-inflammatory cytokines like TNF-α that further impair leptin signaling." (PMID 40699756, 2025). "However, several studies have highlighted leptin as an adipokine with both systemic and obesity-independent effects, acting as a potent anti-apoptotic, proliferative, and inflammatory agent, which significantly influences the immune response and thus may directly impact tumorigenesis." (PMID 40427173, 2025). "An increase in leptin, insulin, and IGF-1 and a reduction in ghrelin were established in previous studies of patients affected by OW and I–II stages of obesity." (PMID 39970875, 2025).